LCE2D (late cornified envelope 2D)
Description:
Precursors of the cornified envelope of the stratum corneum.
Synonyms: LEP12; SPRL1A
Tractability: No criterion of Open Targets' tractability assessment is met for any kind of drug.
Gene: Protein-coding gene on chromosome 1 (152,663,380 to 152,664,659, forward strand). Ensembl gene ENSG00000187223.
Pathways (Reactome):
Developmental Biology: Formation of the cornified envelope
Gene Ontology:
Molecular function: protein binding
Biological process: epidermis development
Genetic constraint (gnomAD): Loss-of-function variants: 0 observed, 0.59 expected, observed/expected ratio (o/e) 0, 90% interval 0 to 1.82. That is too few expected variants to judge how well the gene tolerates losing a copy. Missense variants: 161 observed, 146.55 expected, observed/expected ratio (o/e) 1.1, 90% interval 0.97 to 1.25. Synonymous variants: 55 observed, 52.88 expected, observed/expected ratio (o/e) 1.04, 90% interval 0.84 to 1.3.
Homologues: Paralogues in human: LCE2C (96% identical), LCE2B (95% identical), LCE2A (88% identical), LCE1E (75% identical), LCE1F (75% identical), LCE5A (75% identical), LCE1D (74% identical), LCE3D (55% identical), LCE3B (53% identical), LCE3E (53% identical), LCE3A (50% identical), LCE3C (50% identical), and 8 more.